SIAE (sialic acid acetylesterase)
Description:
Catalyzes the removal of O-acetyl ester groups from position 9 of the free diacetylated sialate N-acetyl-9-O-acetylneuraminate (Neu5,9Ac2) in the cytosol and of the diacetylated sialate residues of sialylglycoconjugates in the lysosomes (Probable). Together with the sialate-O-acetyltransferase they regulate the balance of acetylated sialoglycoconjugates, key players in various processes such as cell-cell interactions, host-pathogen recognition, and tumor antigenicity.
Synonyms: YSG2; CSE-C; MGC87009; LSE; AIS6; CSEC
Tractability: Antibody: UniProt predicts a signal peptide or a membrane-spanning region. PROTAC: its protein half-life has been measured.
Target class: Enzyme; Hydrolase
Gene: Protein-coding gene on chromosome 11 (124,633,113 to 124,695,707, reverse strand). Ensembl gene ENSG00000110013.
Subcellular location: Lysosome (Isoform 1); Cytoplasm (Isoform 2)
Gene Ontology:
Molecular function: protein binding; sialate O-acetylesterase activity; sialate 9-O-acetylesterase activity
Biological process: carbohydrate metabolic process; regulation of immune system process
Cellular component: extracellular exosome; extracellular region; cytoplasm; lysosome
Genetic constraint (gnomAD): Loss-of-function variants: 38 observed, 52.84 expected, observed/expected ratio (o/e) 0.72, 90% interval 0.55 to 0.94. The upper end of that interval is the gene's LOEUF score, 0.94, which puts it in group 4 of 6, group 1 being the genes least tolerant of losing a copy. Missense variants: 590 observed, 698.58 expected, observed/expected ratio (o/e) 0.84, 90% interval 0.79 to 0.9. Synonymous variants: 233 observed, 256.23 expected, observed/expected ratio (o/e) 0.91, 90% interval 0.82 to 1.01.
Homologues: Orthologues: chimpanzee SIAE (99% identical), macaque SIAE (97% identical), guinea pig SIAE (80% identical), pig SIAE (79% identical), mouse Siae (79% identical), rat Siae (78% identical), rabbit SIAE (72% identical), dog SIAE (71% identical), tropical clawed frog siae (52% identical), zebrafish siae (47% identical).
Diseases named in the same sentence as SIAE in open-access papers:
SIAE is named in the same sentence as 10 diseases in open-access papers, as found by Europe PMC text mining. Sharing a sentence is not in itself a finding about the gene and the disease. The quoted sentences say what the papers report.
colon cancer (1 paper, 2023). "We employed lung cancer (A549) and colon cancer (HCT 116) cells whose sialate O-acetyl transferase (CASD1) gene and sialate O-acetyl esterase (SIAE) gene have been removed via CRISPR Cas 9 gene editing." (PMID 37377914, 2023).
glioma (1 paper, 2020). A benign or malignant brain and spinal cord tumor that arises from glial cells (astrocytes, oligodendrocytes, ependymal cells). "PE‐Sun, which consists of three pathway‐extended genes, SIAE, NR4A1 and EPHA2, was evaluated in gliomas." (PMID 34766125, 2020).
lung carcinoma (1 paper, 2021). "Furthermore, knock out of Sialic acid acetylesterase resulted in enhanced NK cell-mediated cytotoxicity in colon and lung cancer cells." (PMID 34966391, 2021).
mild cognitive impairment (1 paper, 2025). "Endo-lysosomal proteins (e.g., HEXB, TPP1, SIAE) increased early in abundance alongside neurodegeneration-related proteins, and were followed by increases in metabolic proteins such as ALDOA, MDH1, and GOT1 at the mild cognitive impairment (MCI) stage." (PMID 40329321, 2025).
thyroid disease (1 paper, 2022). "No previous association with thyroid disease has been reported for the remaining five proteins: sialic acid acetylesterase (SIAE), hepatocyte growth factor-regulated tyrosine kinase substrate (HGS), Myotrophin (MTPN), 60S ribosomal protein L24 (RPL24), and Coronin-7 (CORO7)." (PMID 36068205, 2022).
tumor (4 papers, 2014 to 2025). "NAB2, CYP27A1, NPIPB4, MAOB, and SIAE, demonstrated lower expression for the OSCC group compared with a non-tumor group." (PMID 40723410, 2025). "CDCA7, CELSR3, PACS1, SNTB1, and TBC1D31 showed consistent upregulation in CRC tumor samples and pre-surgical cfRNA, while GFI1B, HPGD, SH3BGRL2, SIAE, PKHD1L1, and TDP2 showed downregulation in CRC tumor samples and pre-surgical cfRNA." (PMID 37091184, 2023).
cancer (2 papers, 2020 to 2024). A tumor composed of atypical neoplastic, often pleomorphic cells that invade other tissues. "Knocking out SIAE gene generated cancer cells with O-acetylated sialic acid, while knocking out CASD1 gene resulted in cancer cells with de-O- acetylated sialic acid." (PMID 39717751, 2024).
SIAE also shares sentences with these, for which no sentence is quoted: infection (1 paper); obstructive hydrocephalus (1); rheumatoid arthritis (1).